TEKT4 (tektin 4)
Description:
Microtubule inner protein (MIP) part of the dynein-decorated doublet microtubules (DMTs) in cilia and flagellar axoneme. Forms filamentous polymers in the walls of ciliary and flagellar microtubules (By similarity). Contributes to normal sperm motility (By similarity).
Synonyms: MGC27019
Tractability: Small molecule: a structure with a bound ligand is known. PROTAC: UniProt records ubiquitination sites on it.
Gene: Protein-coding gene on chromosome 2 (94,871,430 to 94,876,823, forward strand). Ensembl gene ENSG00000163060.
Subcellular location: Cytoplasm, cytoskeleton, cilium axoneme; Cytoplasm, cytoskeleton, flagellum axoneme
Subcellular location (Human Protein Atlas): Annulus; Connecting piece; End piece; Flagellar centriole; Perinuclear theca; Principal piece
Gene Ontology:
Molecular function: protein binding
Biological process: cilium assembly; cilium movement involved in cell motility; flagellated sperm motility
Cellular component: axonemal microtubule; nucleus; sperm end piece; sperm principal piece; axonemal A tubule inner sheath; microtubule cytoskeleton; sperm flagellum; axoneme; cilium; cytoplasm
Genetic constraint (gnomAD): Loss-of-function variants: 46 observed, 41.38 expected, observed/expected ratio (o/e) 1.11, 90% interval 0.88 to 1.42. The synonymous counts are far from expectation, so gnomAD's model fits this gene poorly and the ratio says little. Missense variants: 790 observed, 605.36 expected, observed/expected ratio (o/e) 1.3, 90% interval 1.23 to 1.38. Synonymous variants: 325 observed, 257.34 expected, observed/expected ratio (o/e) 1.26, 90% interval 1.15 to 1.38.
Homologues: Orthologues: chimpanzee TEKT4 (98% identical), macaque TEKT4 (93% identical), mouse Tekt4 (77% identical), rat Tekt4 (76% identical), dog TEKT4 (71% identical), tropical clawed frog tekt4 (61% identical), zebrafish tekt4 (52% identical), Drosophila melanogaster Tektin-A (29% identical), Caenorhabditis elegans R02E12.4 (23% identical). Paralogues in human: TEKT3 (38% identical), TEKT1 (36% identical), TEKT5 (34% identical), TEKT2 (29% identical), MAFIP (23% identical).
Diseases named in the same sentence as TEKT4 in open-access papers:
TEKT4 is named in the same sentence as 8 diseases in open-access papers, as found by Europe PMC text mining. Sharing a sentence is not in itself a finding about the gene and the disease. The quoted sentences say what the papers report.
breast carcinoma (3 papers, 2021 to 2025). "Research has shown that breast cancer cells harboring Tekt4 germline mutations were associated with resistance to paclitaxel-based chemotherapy by stabilizing the tubulin structure in doublet microtubules." (PMID 39949046, 2025). "Pre-mRNA mutations in Tekt1, Tekt4, and Tekt5 are strongly correlated with the occurrence of civil dyskinesia, breast cancer, and coronary artery disease, respectively." (PMID 39949046, 2025). "This is consistent with prior research showing that TEKT4 loss relates to breast cancer metastasis." (PMID 36700111, 2021). "Further sequencing confirmed the Tekt4 status in an additional 24 breast cancer samples and revealed that after NCT, the original genotype was maintained in 74 cases (88.1%), whereas the Tekt4 variations c." (PMID 39949046, 2025). "Breast cancer cells with these Tekt4 variations are relatively sensitive to the antitumour drug vinorelbine (a microtubule-depolymerizing agent)." (PMID 39949046, 2025). "Individual Tekt proteins may also play distinct roles in specific biological processes, such as Tekt2 in photoreceptor survival, Tekt4 in breast cancer, and Tekt5 in sperm formation and cancer cell survival." (PMID 39949046, 2025). "Furthermore, they reported that Tekt4 germline variations were enriched in posttreatment breast cancer tissues." (PMID 39949046, 2025). "Moreover, Tekt4 plays a crucial role in microtubule stability and breast cancer sensitivity to drugs." (PMID 39949046, 2025).
asthenozoospermia (1 paper, 2020). "We have previously reported on genes whose KO led to asthenozoospermia, such as Tektin 3 (TEKT3), Tektin 4 (TEKT4), T-complex-associated-testis-expressed 1 (TCTE1), and T-complex 11 (TCP11), with each having unique roles in sperm motility." (PMID 32588889, 2020).
tumor (5 papers, 2014 to 2025). "Among the 5,291 coding somatic mutations found in an aggregate of 240 matched tumour/normal samples, we found 26 overlapping variants in SH-SY5Y inside 24 genes among which 9 were rare amino-acid changing mutations inside 7 genes (ALK, FOXD4L1, HLA-DRB1, NBPF10, NBPF14, PABPC3, TEKT4)." (PMID 25528190, 2014).
cancer (1 paper, 2025). A tumor composed of atypical neoplastic, often pleomorphic cells that invade other tissues. "Furthermore, the role of Tekt4 in thyroid tumourigenesis and the influence of Tekt5 on cell cycle regulation in ovarian cancer cells highlight a significant connection between Tekt proteins and the development of cancer." (PMID 39949046, 2025).
neurodevelopmental disorder (1 paper, 2023). A behavioral and cognitive disorder with onset during the developmental period that involves impaired or aberrant development of intellectual, motor, or social functions. "A missense variant in TEKT4 was discovered in a family with PSMD12 haploinsufficiency, a neurodevelopmental disorder with autistic features." (PMID 37872607, 2023).
TEKT4 also shares sentences with these, for which no sentence is quoted: developmental delay (1 paper); neurological disorders (1); schizophrenia (1).